CARD14 (caspase recruitment domain family member 14)
Diseases named in the same sentence as CARD14 in open-access papers (continued):
Sharing a sentence is not in itself a finding about the gene and the disease.
psoriasis (continued). "Genes CARD14, REL, TNIP1/ANXA6, TNFAIP3, UBE2L3, CARM1, NFKBIA and FBXL19 have been revealed to be involved in the NF-κB signaling pathway of psoriasis." (PMID 29232931, 2017). "In conclusion, we have determined that CARD14, the gene responsible for PSORS2, is expressed dermally in both blood and lymphatic ECs, as well as in aortic ECs, the latter of which may prove to be an interesting link to the cardiovascular comorbidities associated with psoriasis." (PMID 25369198, 2014). "When comparing psoriasis-involved skin to the adjacent normal skin of patients with psoriasis, differentially methylated CpGs are found, some of which situated at the promoters of known PSORS genes, such as S100A9, PTPN22, SELENBP1, CARD14, and KAZN." (PMID 37628670, 2023). "Unlike PSORS1C3 gene, reports on the effects of CARD14 and TLR4 haplotypes in psoriasis susceptibility are limited." (PMID 36382932, 2022). "Interestingly, we demonstrated that all the three haplotypes (A-G, GA-GA and G-T-T) in PSORS1C3 gene, the AG-CT-C haplotype in CARD14 gene and the T-T-T haplotype in TLR4 gene were detected at higher frequencies in patients with psoriasis compared to controls." (PMID 36382932, 2022). "Consequently, CARD14 has definitive and multiple roles in the cascade/loop of IL-17–TRAF6-mediated chronic inflammation in the skin of psoriasis patients." (PMID 31156649, 2019). "This healthy carrier from the Eskin-Schwartz report is negative for the three additional CARD14 variants and for the 06:02 allele at the HLA-C locus, suggesting that genetic cofactors as well as environmental triggers might be required for CARD14-induced psoriasis." (PMID 30386326, 2018). "Additionally, phosphorylated NF-κB was found in psoriatic CARD14+ CD31+ ECs, demonstrating this pathway is active in dermal ECs in psoriasis." (PMID 25369198, 2014). "Consequently, inhibiting MALT1 to block CARD14 signalling in psoriasis may also not be a viable option." (PMID 39145956, 2024). "In recent studies comparing psoriasis-involved skin to adjacent non-lesional skin, differences in CpG methylation were found at the promoters of known PSORS genes, such as S100A9, PTPN22, SELENBP1, CARD14, and KAZN." (PMID 38256115, 2024).
plaque psoriasis (16 papers, 2019 to 2025). "The results highlighted a significant correlation between the CARD14 gene and the predisposition to psoriasis vulgaris in the Han population." (PMID 40343299, 2025). "In another case report, a patient diagnosed with ILVEN in childhood and later developed psoriasis vulgaris elsewhere was found to have a germline CARD14 pathogenic variant." (PMID 40103681, 2025). "Mutations in CARD14 manifest clinically in various forms, including as psoriasis vulgaris (PsV), PRP, and GPP, with diverse phenotypic expressions, even from identical mutations." (PMID 39373130, 2024). "CARD14 mediates NF-κB signaling in keratinocytes; gain of function mutations here are strongly implicated in plaque psoriasis pathogenesis, whereas missense variants only seem to increase the risk of pustular psoriasis with concurrent plaque psoriasis." (PMID 38785955, 2024). "Our study was designed to assess the association between CARD14 gene polymorphisms and psoriasis vulgaris in the Hainan Han population." (PMID 36221432, 2022). "Rare gain-of-function mutations in the gene that encodes the keratinocyte signaling molecule (CARD14) were found to be causative of familial psoriasis vulgaris and familial pityriasis rubra pilaris in 2012." (PMID 34445754, 2021). "The CARD14 mutation has also been found primarily in patients with generalized pustular psoriasis and plaque psoriasis." (PMID 34884596, 2021). "Many GPP patients carrying CARD14 variants also have plaque psoriasis." (PMID 39698752, 2025). "Activating mutations of CARD14 (caspase recruitment domain family member 14), which codes for an inductor of NF-kB signaling expressed in keratinocytes, have also been observed in plaque psoriasis, psoriatic arthritis, and generalized (as well as localized) pustular psoriasis." (PMID 38256115, 2024). "CARD14 gene is associated with susceptibility to psoriasis vulgaris in the Hainan Han population." (PMID 36221432, 2022). "Indeed, CARD14 mutations are associated with both psoriasis vulgaris and GPP, with the strongest CARD14 activity causing GPP." (PMID 32153585, 2020). "This study aimed to determine whether the CARD14 gene is a susceptible gene for psoriasis vulgaris." (PMID 36221432, 2022). "We have previously shown that rare, gain-of-function and highly penetrant (>90%) alterations within the Caspase recruitment domain-containing protein 14 (CARD14) gene can promote the development of psoriasis vulgaris (plaque psoriasis) and psoriatic arthritis." (PMID 39145956, 2024). "Mutations in CARD14 gene account for only a small proportion of cases of GPP; in most cases they are present in GPP patients with concomitant psoriasis vulgaris, but were only rarely identified in GPP alone." (PMID 34445754, 2021). "No mutations of the CARD14 gene that are specific to patients suffering from psoriasis vulgaris and GPP have yet been found." (PMID 34445754, 2021). "Furthermore, both the CARD14 pathway and the IL36RN pathway are associated not only with GPP, but also with psoriasis vulgaris." (PMID 32153585, 2020).
generalized pustular psoriasis (15 papers, 2018 to 2025). A rare and extreme form of psoriasis characterized by the appearance of sterile pustules which can take many patterns. "The most common mutation in generalized pustular psoriasis occurs in the IL-36 receptor antagonist gene, though rarer mutations include pathogenic CARD14, AP1S3, and MPO genes." (PMID 39802942, 2025). "To date, CARD14 gene mutations have been associated with various diseases that produce widespread pustular rashes, such as generalized pustular psoriasis (GPP), psoriatic arthritis, and pityriasis rosea." (PMID 37089611, 2023). "Autosomal dominant gain of function mutations in caspase recruitment domain family member 14 (CARD14) is a rare condition associated with plaque-type psoriasis, generalized pustular psoriasis, palmoplantar pustular psoriasis and pityriasis rubra pilaris." (PMID 31286971, 2019). "Recent identification of CARD14 as the psoriasis susceptible gene 2 and IL36RN mutations in generalized pustular psoriasis have defined new entities, CARD14-associated psoriasis (CAMPS) and deficiency of interleukin-36 receptor antagonist (DITRA), respectively." (PMID 32256502, 2020).
pustular psoriasis (15 papers, 2015 to 2025). "Other genes with mutations associated with pustular psoriasis include caspase-activating recruitment domain member 14 (CARD14), adaptor protein complex 1 subunit sigma 3 (AP1S3), TNFAIP3-interacting protein 1 (TNIP1), and serpin family A member 3 (SERPINA 3)." (PMID 33919434, 2021). "A likely pathogenic nonsynonymous variant rs200731780 (c.452G>A: p.R151Q) in the CARD14 gene associated with CARD14-mediated pustular psoriasis (CAMPS) that has been predicted as benign by computational prediction tools." (PMID 34905135, 2021). "Gain-of-function mutations of CARD14 activate the NF-κB signal transduction pathway, and increased NF-κB activity due to CARD14 mutations is shown to be linked to pustular psoriasis." (PMID 31902555, 2020). "Therefore, IL-36RN-associated GPP, and CARD14-mediated pustular psoriasis, PRP type V and familial keratosis lichenoides chronica (KLC) caused by NLRP1 mutation, can be considered AIKDs." (PMID 30386326, 2018). "The only other known gene for pustular psoriasis (CARD14) is also abundantly expressed in keratinocytes, suggesting that these cells play an important role in cutaneous autoinflammation." (PMID 27388993, 2016). "The main genes implicated in pustular psoriasis are IL36RN, CARD14, and AP1S3." (PMID 38785955, 2024). "IL36RN mutations are the genetic variant most frequently observed in patients with pustular psoriasis (5–24%), followed by AP1S3 in 7–11% and CARD14 in a very small number of subjects; the highest rates correspond to patients with GPP, and the lowest correspond to PPP in all cases." (PMID 33919434, 2021). "However, recently, pustular psoriasis has been associated with mutations in AP1S3, CARD14, and IL356RN." (PMID 34884596, 2021). "In 2014, mutations in AP1S3, the gene encoding AP-1 complex subunit sigma 3, were found in unrelated individuals with severe pustular psoriasis, including patients with GPP not harboring IL36RN and CARD14 mutations." (PMID 34445754, 2021).
pityriasis rubra pilaris (9 papers, 2018 to 2025). A group of skin conditions that cause constant inflammation and scaling of the skin. "Familial pityriasis rubra pilaris (PRP) is commonly caused by heterozygous GOF mutations of CARD14, which is a regulator of nuclear factor-κB (NF-κB-) signalling." (PMID 35069188, 2021). "Interestingly, one of those CARD14 variants was previously reported to cause pityriasis rubra pilaris (PRP) when present as a germline mutation." (PMID 40103681, 2025). "CARD14 mutations have also been associated with pityriasis rubra pilaris (PRP)." (PMID 31286971, 2019). "Furthermore, a report from the Sprecher group broadened the occurrence of CARD14 mutations to pityriasis rubra pilaris (PRP), a rarer form of psoriatic skin disease." (PMID 30386326, 2018).
inflammatory skin disorders (8 papers, 2018 to 2025). "CARD14 GOF variants are linked to inflammatory skin disorders, particularly a unique combination of features resembling psoriasis and pityriasis rubra pillars, which is known as CARD14-associated papulosquamous eruption (CAPE)." (PMID 39859044, 2025). "CARD11 mutations are linked to lymphoproliferative disorders and immunodeficiencies, whereas CARD14 variants are associated with several inflammatory skin disorders." (PMID 36618379, 2022). "The regulatory role of inflammatory skin disorders is reported mediated through CARD14 signaling." (PMID 36382932, 2022). "In this review, we provide an overview on the molecular mechanisms mediating CARD14/CARMA2 signaling and its implication in our understanding of the pathogenesis of human inflammatory skin disorders." (PMID 30319628, 2018).
skin inflammation (5 papers, 2024 to 2025). "Dysfunction of the IL‐36 receptor antagonist (IL‐36Ra), encoded by IL36RN, initiates a downstream inflammatory cascade, while activation of CARD14, encoded by CARD14, promotes skin inflammation by activating NF‐κB in epidermal keratinocytes." (PMID 39373130, 2024). "CARD14 is an intracellular scaffold protein that is predominantly expressed in skin keratinocytes, where it has been shown to control skin inflammation." (PMID 41131424, 2025). "CARD14, belonging to both inflammation and dermatitis pathways, was also upregulated." (PMID 41416938, 2025). "CARD14, similar to CARD11, activates NF-κB signaling but in keratinocytes, contributing to skin inflammation and hyperplasia." (PMID 39859044, 2025). "Tamoxifen-induced expression of CARD14E138A in Card14LSL-E138A mice rapidly induces TNF-dependent psoriasiform skin inflammation, which is independent of adaptive immune cells and due to signalling in keratinocytes, which express high levels of CARD14." (PMID 39145956, 2024).
atopic dermatitis (3 papers, 2019 to 2025). "It is of interest to note that loss-of-function mutations in CARD14 have been reported in 3 families with a severe variant of atopic dermatitis whereas Card14−/− mice do not have spontaneous AD." (PMID 31156649, 2019).
breast carcinoma (2 papers, 2021 to 2023). "Knockdown of CARD14 can prevent breast cancer cells from proliferating and migrating, stop the cell cycle at the G1/S juncture, and increase cell death." (PMID 36673815, 2023). "In particular, it was shown that CARD14 resulted overexpressed in breast cancer cell lines, and its knockdown led to decreased breast cancer cell proliferation and migration ability, accompanied by the induction of cell death through NF-ĸB." (PMID 34012923, 2021).
keratinization disease (2 papers, 2018 to 2020). "CARD14 mutations have been previously linked to type V PRP, which, due to the autoinflammatory pathogenic mechanism caused by mutation to CARD14, was recently characterized by Akiyama and colleagues as "autoinflammatory keratinization diseases"." (PMID 30018619, 2018).
prostate carcinoma (2 papers, 2005 to 2022). A carcinoma that arises from epithelial cells of the prostate gland. "The increased expression of CARD14 may facilitate the activation of NF-κB in prostate cancer." (PMID 16042785, 2005). "In a practical application of multiple expression-platform profiling, our analysis of C4-2 and LNCaP prostate cancer cell lines has identified genes such as CA1, CARD14, and EPHA7 that may be involved in prostate cancer progression." (PMID 16042785, 2005).
colitis (1 paper, 2025). Inflammation of the colon. "These mice show mild intestinal inflammation, underscoring a possible link between dysregulated CARD14 signaling and colitis." (PMID 41131424, 2025).
COVID-19 (1 paper, 2022). A disease caused by infection with severe acute respiratory syndrome coronavirus 2. "Among the COVID-19 differentially methylated loci detected in blood, we observed hypermethylation related to the caspase recruitment domain family member 14 (CARD14) gene." (PMID 35719387, 2022).
disc degeneration (1 paper, 2019). "Interestingly, we identified three hypermethylated genes in the advanced stage of disc degeneration (CARD14, EFHD2 and RTKN2) that are involved in the regulation of the NF-κB pathway." (PMID 31513634, 2019).
erythroderma (1 paper, 2024). "The patient had mutations IL36RN and CARD14, but it was unclear whether either mutation was associated with her erythroderma." (PMID 39373130, 2024). "We present a patient with erythroderma with heterozygous mutations in IL36RN and CARD14, characterized by multiple lesions displaying what appeared to be normal‐looking spots." (PMID 39373130, 2024).
Fanconi anemia (1 paper, 2022). Fanconi anemia (FA) is a hereditary DNA repair disorder characterized by progressive pancytopenia with bone marrow failure, variable congenital malformations and predisposition to develop hematological or solid tumors. "Several DDR pathways including Fanconi anemia, base excision repair, translesional synthesis, damage sensor, homologous recombination, mismatch repair, and direct repair were found to be positively correlated with CARD14 expression." (PMID 36009554, 2022).
gastric cancer (1 paper, 2021). A primary or metastatic malignant neoplasm involving the stomach. "In summary, we have identified a group of genes differentially regulated in the intestinal and diffuse histotypes of gastric cancers with AQP9, CARD14 and CXCR2 impacting on patients’ prognosis, although CXCR2 is the only factor independently impacting overall survival." (PMID 34012923, 2021). "For these reasons, our results suggest that FPR2, CARD14, CXCR2, EFNA2, CXCR1, AQP9 TRIP13, along with GHRL and KLK11, could be used as promising biomarkers for gastric cancer diagnosis or prognostic evaluation." (PMID 34012923, 2021).
Immunodeficiency (1 paper, 2022). Failure of the immune system to protect the body adequately from infection, due to the absence or insufficiency of some component process or substance. "With this consideration, we have noted the presence of rare variants in other immunodeficiency genes (JAK2, JAK3, IL17RA, IL12RB2, CARD14, and TYK2) in our various patients, which could feasibly contribute to the penetrance and/or differences in the clinical phenotypes of the patients." (PMID 36672844, 2022).
intestinal infection (1 paper, 2025). "We next hypothesized that reduced AMP expression might increase the susceptibility of CARD14(E138A)IEC mice to intestinal infection." (PMID 41131424, 2025).
migraine (1 paper, 2020). "If mutations within the PRE results in increased expression of CARD14, it could therefore cause an increased activation of NF-κB and thus influence migraine." (PMID 32076896, 2020).
ovarian carcinoma (1 paper, 2020). A malignant neoplasm originating from the surface ovarian epithelium. "In ovarian cancer, PROM2 is slightly co-expressed with CARD14." (PMID 31164716, 2020).
Psoriasiform dermatitis (1 paper, 2024). A skin abnormality characterized by redness and irritation, with thick, red skin that displays flaky, silver-white patches (scales). "CARD14E138A was chosen as this mutation leads to higher levels of NF-κB activation than other mutations and mouse studies have demonstrated that Card14 E138 mutations induce a psoriasiform dermatitis that is strikingly similar to human psoriatic skin." (PMID 39145956, 2024). "Rapamycin inhibition of mTORC1 signalling impairs the development of imiquimod-induced psoriasiform dermatitis in mice, which is partially dependent on CARD14 expression." (PMID 39145956, 2024).
Rectal prolapse (1 paper, 2025). Protrusion of the rectal mucous membrane through the anus. "As rectal prolapse is often associated with pathological conditions that increase intra-abdominal pressure, such as constipation, we reasoned that CARD14(E138A) expression in IEC might influence intestinal motility." (PMID 41131424, 2025). "Moreover, CARD14(E138A)IEC mice show a drastic reduction in intestinal motility, often associated with rectal prolapse." (PMID 41131424, 2025). "Surprisingly, 31% of CARD14(E138A)IEC mice developed rectal prolapse at the age of 5–7 weeks." (PMID 41131424, 2025).
rheumatoid arthritis (1 paper, 2023). A chronic, systemic autoimmune disorder characterized by inflammation in the synovial membranes and articular surfaces. "Our report describes a patient with rheumatoid arthritis and AGEP associated with hydroxychloroquine and a newly discovered CARD14 gene mutation." (PMID 38013380, 2023).
skin infection (1 paper, 2018). An inflammatory process affecting the skin, caused by bacteria, viruses, parasites, or fungi. "Utilizing CARD14-deficient mice in skin infection or barrier disruption models will lead to a greater understanding of how this molecule is activated and mounts an innate immune response to infection." (PMID 30386326, 2018).
skin reaction (1 paper, 2018). "The individual contributions of keratinocytes and γδ T cells to the CARMA2/CARD14 dependent-inflammation and the extent to which MALT1 protease activity contributes to inflammatory skin reactions remain to be further investigated." (PMID 30214442, 2018).
ulcerative colitis (1 paper, 2025). An inflammatory bowel disease involving the mucosal surface of the large intestine and rectum. "Apart from the observation that CARD14 expression is increased in ulcerative colitis patients and positively correlates with disease severity, its functional role in the gut is largely uncharacterized." (PMID 41131424, 2025). "Increased CARD14 expression has previously been shown to positively correlate with disease severity in ulcerative colitis patients." (PMID 41131424, 2025).
infection (5 papers, 2018 to 2025). The state of being infected such as from the introduction of a foreign agent such as serum, vaccine, antigenic substance or organism. "Among genes associated with pathogen recognition, CARD14 was most prominently up-regulated during clade I and IV infection at 48 HPI, while NLRP3 (a key inflammasome component) was expressed during clade III infection at 24 HPI." (PMID 41419766, 2025). "Within the same protein family, downregulation of CARD14 was reported to lead to severe AD and reduced skin protection against infection as well as dysregulated cutaneous inflammation pathways." (PMID 32325630, 2020). "It showed upregulation of multiple inflammatory transcripts, including Toll-like receptor 1/2 (TLR1/2), CD69, and CARD14, upon 5-ASKH infection." (PMID 36190414, 2022).